GADD45G (growth arrest and DNA damage inducible gamma)
Diseases named in the same sentence as GADD45G in open-access papers (continued):
Sharing a sentence is not in itself a finding about the gene and the disease.
lung carcinoma (3 papers, 2015 to 2021). "Downregulation of GADD45G by aberrant promoter methylation has been noted in esophageal, colorectal, pancreatic, cervical, and lung cancer." (PMID 34299042, 2021).
ovarian carcinoma (3 papers, 2007 to 2025). A malignant neoplasm originating from the surface ovarian epithelium. "NAC1-mediated downregulation of GADD45G has been shown to contribute to paclitaxel resistance in ovarian cancer cells." (PMID 41018072, 2025). "In this study, we analyzed the mechanism of reversion of paclitaxel resistance by CRM197 and identified a signaling axis involving NAC‐1/Gadd45gip1/Gadd45γ, which appears to enhance activities of the proapoptotic JNK/p38MAPK pathway that induces paclitaxel resistance in ovarian cancer." (PMID 31490008, 2019).
prostate carcinoma (3 papers, 2015 to 2025). A carcinoma that arises from epithelial cells of the prostate gland. "Other studies have also suggested that GADD45G, a novel vitamin D-regulated gene, exerts anti-proliferative effects in prostate cancer cells." (PMID 41018072, 2025). "In addition, c-Myc suppresses GADD45g gene expression in prostate cancer cells." (PMID 38582902, 2024).
atherosclerosis (2 papers, 2022 to 2025). A disease characterized by the build-up of fatty material and calcium deposition in the arterial wall resulting in partial or complete occlusion of the arterial lumen. "Therefore, the protective role of miR-15b-5p in atherosclerosis is directly associated with GADD45G." (PMID 35137664, 2022). "In conclusion, circCHFR promotes atherosclerosis progression via the miR-15b-5p/GADD45G axis and may be an important target for atherosclerosis treatment." (PMID 35137664, 2022). "Therefore, it is worthwhile to explore the function of GADD45G in atherosclerosis." (PMID 35137664, 2022). "We also investigated the abundance of circCHFR, miR-15b-5p, and GADD45G in ox-LDL-treated HUVECs and their involvement in atherosclerosis, as well as the mechanism by which circCHFR contributes to atherosclerosis development via the miR-15b-5p/GADD45G axis." (PMID 35137664, 2022).
colon carcinoma (2 papers, 2010 to 2024). "In summary, we found that shikonin suppresses colon cancer cell proliferation and migration through cellular experiments and identified eight genes (CCNB3, IL-1α, CXCL8, CDKN2A, MYC, IGFBP3, SQSTM1, and GADD45G) associated with cell senescence through systematic bioinformatics analysis." (PMID 39188951, 2024). "In GANT61-treated human colon carcinoma cells, novel DNA damage-inducible transcripts DDIT3 (GADD153), DDIT4 (REDD1), DDIT2 (GADD45G), PPP1R15A (GADD34) and ATF3 were significantly up-regulated concomitant with the arrest of cells at G1/S." (PMID 20957031, 2010).
COVID-19 (2 papers, 2022). A disease caused by infection with severe acute respiratory syndrome coronavirus 2. "Also, GADD45G, HRK, and BAK, as proapoptotic proteins, showed a significant increase with severity in COVID-19." (PMID 35573725, 2022).
diffuse large B-cell lymphoma (2 papers, 2015 to 2021). "The frequency of GADD45γ methylation and the epigenetic change of GADD45γ might be related to the progress of diffuse large B‐cell lymphoma." (PMID 33080073, 2021).
embryonal carcinoma (2 papers, 2008 to 2013). A non-seminomatous malignant germ cell tumor characterized by the presence of large germ cells with abundant cytoplasm resembling epithelial cells, geographic necrosis, high mitotic activity, and pseudoglandular and pseudopapillary structures formation. "Mash1 also rapidly induces expression of Gadd45g and Mfng in the embryonal carcinoma cell line P19, as detected by quantitative reverse transcription polymerase chain reaction (RT-PCR)." (PMID 18377642, 2008).
endometrial cancer (2 papers, 2022 to 2023). Primary or metastatic malignant neoplasm involving the endometrium (mucous membrane that lines the endometrial cavity). "Among them, we identified four genes (SFN, CDKN1A, GADD45G, and TP73) whose expression was positively correlated with endometrial cancer from TCGA data." (PMID 36358786, 2022).
heart failure (2 papers, 2020 to 2023). Inability of the heart to pump blood at an adequate rate to meet tissue metabolic requirements. "Recent studies have reported that GADD45G overexpression in mice induced cardiomyocyte apoptosis, fibrosis, LV dysfunction, and heart failure, whereas GADD45G deletion conferred resistance to ischemic injury and cardiomyocyte apoptosis." (PMID 32138671, 2020).
infertile (2 papers, 2009 to 2020). "For example, three possible target genes for down-regulated miRNAs, TIMP3, SOX9 and GADD45G, were significantly increased in infertile testis." (PMID 19210773, 2009).
liver cancer (2 papers, 2023). An epithelial or non-epithelial malignant neoplasm that arises from the liver. "In recent years, a number of studies have tried to clarify the relationship between GADD45G and liver cancer." (PMID 37833694, 2023). "In short, 4MOD significantly inhibited the growth of human liver cancer cells in vitro by targeting GADD45G." (PMID 36776954, 2023). "We determined that 4MOD significantly inhibited human liver cancer cells' proliferation and migration, as well as promoting cell apoptosis through upregulation of GADD45G in vitro." (PMID 36776954, 2023). "Eventually, the exact function and molecular mechanism of GADD45G in liver cancer require further exploration." (PMID 37833694, 2023). "It was found that the AUC value was 0.80 (95% CI = 0.76–0.83), suggesting that GADD45G mRNA had a moderate ability to distinguish liver cancer from normal liver tissues." (PMID 37833694, 2023). "A previous study reported that GADD45G mRNA expression was downregulated in liver cancer and could induce cell cycle G2/M phase arrest, thus playing a significant role in cell growth." (PMID 37833694, 2023). "Moreover, this study confirms that 4MOD inhibits the growth of liver cancer in vivo through upregulating GADD45G, which increases our understanding of the anti-tumor effect and mechanism of 4MOD in HCC." (PMID 37833694, 2023). "GADD45G expression can be used as a new clinical biomarker for HCC and GADD45G may be a potential target for the anti-cancer effect of 4MOD in liver cancer." (PMID 37833694, 2023). "In light of its critical role in the pathogenesis of liver cancer, GADD45G may be a valuable target for anti-cancer drugs." (PMID 37833694, 2023). "Our findings show that 4MOD elicits anti-HCC effects by upregulating GADD45G expression and could be a valuable anticancer agent for liver cancer." (PMID 36776954, 2023). "In order to further explore the molecular mechanisms of GADD45G in liver cancer, we performed GO and KEGG functional enrichment analysis of 2336 co-expressed genes of GADD45G identified from cBioPortal database." (PMID 37833694, 2023). "However, the specific role of GADD45G in liver cancer remains unclear." (PMID 37833694, 2023).
maturity-onset diabetes (2 papers, 2023 to 2025). "GADD45G was mainly upregulated in maturity-onset diabetes of the young and metabolism and downregulated in the B-cell receptor (BCR), NOD-like receptor (NLR), and Toll-like receptor (TLR) signalling routes." (PMID 37559129, 2023).
pancreatic cancer (2 papers, 2018 to 2022). "We suggest that Gadd45g restrains the interaction between myofibroblast PSCs and pancreatic cancer cells by weakening Stat3 activation during PanIN formation." (PMID 35211358, 2022). "Next, we identified Gadd45g as a novel target gene of miR-301a in both PSCs and pancreatic cancer cell lines." (PMID 35211358, 2022). "Moreover, aberrant PSC expression of miR-301a and Gadd45g restricted the interplay between PSCs and pancreatic cancer cells in tumorigenesis." (PMID 35211358, 2022). "It will therefore be interesting to examine whether Gadd45g is essential for PanIN initiation and pancreatic cancer formation." (PMID 35211358, 2022). "In addition, a positive correlation between Tsc1 and Gadd45g expression was found in pancreatic cancer patients from The Cancer Genome Atlas (TCGA) dataset." (PMID 35211358, 2022). "Our findings suggest that miR-301a activates two major cell proliferation pathways, Tsc1/mTOR and Gadd45g/Stat3, in vivo, to facilitate development of inflammatory-induced PanIN and maintenance of PSC activation and desmoplasia in pancreatic cancer." (PMID 35211358, 2022). "Furthermore, based on TCGA data, a negative correlation between Gadd45g and Stat3 expression was found in pancreatic cancer patients (r = −0.197, p = 0.00831)." (PMID 35211358, 2022).
anaplastic thyroid cancer (1 paper, 2014). "GADD45G is similarly decreased in anaplastic thyroid cancer cells and expression of the gene induces apoptosis." (PMID 25277206, 2014).
asthma (1 paper, 2016). "In contrast, the low-dose preventative administration of IL-27 with multiple administrations could either reverse the impairment of the STAT1 pathway or strengthen the GADD45γ/p38 MAPK pathway and improve the pathologic symptoms of asthma." (PMID 27687913, 2016). "Furthermore, we investigated the effects of preventive and therapeutic IL-27 administration on the allergic airway inflammation in ovalbumin (OVA)-induced asthma mouse models and studied whether the effect is related to the STAT1 and GADD45γ/p38 MAPK pathways." (PMID 27687913, 2016). "In the asthma group, the phosphorylation of STAT1 was impaired, while GADD45γ and p38 MAPK exhibited no obvious changes." (PMID 27687913, 2016). "All of the results suggested that the inflammation existing in the asthma model mainly impaired the phosphorylation of the STAT1 protein, which resulted in the impairment of the STAT1 pathway, and had no obvious effect on the GADD45γ/p38 MAPK pathway." (PMID 27687913, 2016). "We found that the inflammation existing in the asthma model mainly impaired the phosphorylation of the STAT1 protein, which resulted in the impairment of the STAT1 pathway, and had no obvious effect on the GADD45γ/p38 MAPK pathway." (PMID 27687913, 2016).
brain tumors (1 paper, 2025). "Gene profiling revealed that BV2 cells expressed higher levels of both M2‐associated genes (Maf, Selenop, P2ry14, Mrc1, Ctsc, and Cxcr4) and M1‐associated genes (Il7r, Atf3, and Gadd45g) compared to RAW264.7 cells, suggesting its multifaceted role in interaction with brain tumors." (PMID 40747560, 2025).
breast invasive carcinoma (1 paper, 2022). "Consistent with our fly data, in the UALCAN cancer database containing TCGA data, the expression of GLYATL1 and GADD45G are elevated in breast invasive carcinoma, compared with normal tissues." (PMID 35933447, 2022).
Candida infection (1 paper, 2021). "Our genetic analysis suggested that GADD45G from rs10114707 locus that reached genome-wide significance could be a potential core gene that regulates a cytokine network upon Candida infection." (PMID 34512620, 2021). "Therefore, we hypothesized that GADD45G could be a potential core gene that regulates a cytokine network upon Candida infection." (PMID 34512620, 2021).
cervix cancer (1 paper, 2015). "Genes PFDN4, CASP1, PLCE1, ICOSLG, GADD45G, SMARCA2, and TSPO are located in different chromosomes, and there are reports for changes in each one of these chromosomes in cervix cancer, for examples the reader is refer to:." (PMID 26388997, 2015).
chronic kidney disease (1 paper, 2019). Impairment of the renal function secondary to chronic kidney damage persisting for three or more months. "With regard to kidney damage, we previously showed that GADD45γ contributes to the progression of chronic kidney disease in a mouse model of chronic tubular injury and human chronic glomerulonephritis." (PMID 30794682, 2019).
chronic myeloid leukemia (1 paper, 2023). "KEGG analysis in the BaF3-T315 cells showed that the chronic myeloid leukemia signaling pathway (genes such as Cdk4, Tgfbr1, Gadd45b, Mdm2, Gadd45g, Polk, Rb1, Ctbp1, and Cdkn2a were enriched) was involved in the I13 treatment." (PMID 37124196, 2023).
chronic pancreatitis (1 paper, 2022). A chronic inflammatory process causing damage and fibrosis of the pancreatic parenchyma. "We also demonstrate that the protective role of miR-301a deletion in chronic pancreatitis and PanIN is dependent on two downstream axes: Tsc1/mTOR and Gadd45g/Stat3." (PMID 35211358, 2022). "Of note, aberrant regulation of Gadd45g/Stat3 was only found to accelerate PanIN formation but not chronic pancreatitis in mice ablated of miR-301a." (PMID 35211358, 2022).
chronic viral hepatitis (1 paper, 2015). "The expression levels of GADD45γ did not correlate with any clinicopathological factors, including age, sex, underlying chronic viral hepatitis, presence of cirrhosis, tumor grade and stage, serum α-fetoprotein levels, and the presence of vascular invasion." (PMID 26172295, 2015).
Cognitive impairment (1 paper, 2024). Abnormal cognition is characterized by deficits in thinking, reasoning, or remembering. "The upregulation of GADD45γ within the hippocampal dentate gyrus contributes to adaptive responses by facilitating BDNF demethylation; conversely, downregulation of GADD45γ within the hippocampus leads to cognitive impairments and depressive-like behaviors." (PMID 38332860, 2024).
corneal dystrophy (1 paper, 2022). The term corneal dystrophy embraces a heterogeneous group of bilateral genetically determined non-inflammatory corneal diseases that are usually restricted to the cornea. "Therefore, understanding the factors contributing to infectious keratitis, such as GADD45G, NF-κB, and γH2AX signaling, may help to develop antigenotoxic and anti-inflammatory therapies for corneal dystrophy and epithelial cell remodeling." (PMID 35028007, 2022).
cutaneous melanoma (1 paper, 2022). A primary melanoma arising from atypical melanocytes in the skin. "After KD of MAGOH and MAGOHB using the siMAGOH/B Pool, a significant increase in GADD45A mRNA expression was observed in the cutaneous melanoma cell lines Mel Ho and 501Mel, whereas no obvious changes in the expression of GADD45B or GADD45G could be detected." (PMID 36497117, 2022).
Depression (1 paper, 2025). "Least absolute shrinkage and selection operator (LASSO) regression identified five candidate genes (BHLHE41, EPCAM, ADH4, GSTM2, GADD45G) from the Depression and BC datasets." (PMID 40508038, 2025). "In the Depression-GSE169459 validation set, the AUC values were BHLHE41 (0.8667), EPCAM (0.8667), ADH4 (0.5333), GSTM2 (0.9333), and GADD45G (0.8667)." (PMID 40508038, 2025). "In the Depression-GSE76826 dataset, the area under the curve (AUC) values were BHLHE41 (0.8333), EPCAM (0.7500), ADH4 (0.7500), GSTM2 (0.8333), and GADD45G (0.8500)." (PMID 40508038, 2025).
esophageal squamous cell carcinoma (1 paper, 2025). Esophageal squamous cell carcinoma (ESCC) is a type of esophageal carcinoma (EC) that can affect any part of the esophagus, but is usually located in the upper or middle third. "The methylation status and protein expression of GADD45G are significantly associated with the survival of esophageal squamous cell carcinoma (ESCC) patients, while the expression of GADD45A and GADD45B is not." (PMID 41018072, 2025).
glioblastoma (1 paper, 2025). The most malignant astrocytic tumor (WHO grade IV). "Single-cell analysis revealed GADD45G expression patterns and identified its top correlated genes in malignant glioblastoma cells." (PMID 41018072, 2025). "Therefore, we further investigate the relationship between GADD45G and glioblastoma (GBM) by utilizing single-cell data." (PMID 41018072, 2025).
Hepatic fibrosis (1 paper, 2022). The presence of excessive fibrous connective tissue in the liver. "The expression of GADD45G is upregulated in the liver in high-fat-diet-induced non-alcoholic fatty liver disease (NAFLD), and its expression decreases when the high-fat condition is improved, which may be related to its effect of on hepatic fibrosis and the occurrence of chemical transformation." (PMID 35480309, 2022).
Hypertension (1 paper, 2014). The presence of chronic increased pressure in the systemic arterial system. "‘Unknown I’ contained a diverse set of key driver genes such as SGK1, SIK1 and SLC10A6 (sodium metabolism and hypertension), MT2A and TSC22D3 (glucocorticoid signaling), GADD45G, ERRFI1, GPRC5A, and EGFR (cell growth and apoptosis), and CEBPB, CEBPD, and KCNA5 (heart development and function)." (PMID 25033284, 2014).
myelodysplastic syndrome (1 paper, 2021). A clonal hematopoietic disorder characterized by dysplasia and ineffective hematopoiesis in one or more of the hematopoietic cell lines. "Myelodysplastic syndrome cell lines SKM‐1 and HS‐5 were transfected with GADD45γ eukaryotic expression vector and/or GADD45γ shRNA interference plasmid, and treated with azacitidine." (PMID 33080073, 2021).
myeloid malignancies (1 paper, 2024). "We have shown that GADD45g is differentially expressed at low levels in patients with MPN, and cBioPortal analysis revealed that the rates of GADD45g gene mutation are extremely low in various myeloid malignancies (<0.5%), including AML, MPNs and MDSs." (PMID 38582902, 2024). "Therefore, to investigate the role of GADD45g silencing in the pathogenesis of myeloid malignancies, we generated hematopoietic-specific heterozygous (Gadd45g+/−) and homozygous Gadd45g knockout mice (Gadd45g−/−) by crossing Gadd45gflox/flox mice with the Vav-Cre mice." (PMID 38582902, 2024).
myocardial ischemia (1 paper, 2024). A disorder of cardiac function caused by insufficient blood flow to the muscle tissue of the heart. "miR-128-1-5p expression was reduced in mice following myocardial ischemia/reperfusion injury and negatively regulated its direct target Gadd45g, leading to cardiomyocyte apoptosis." (PMID 38542784, 2024).
neuroblastoma (1 paper, 2014). Neuroblastoma (NB) is the most common solid, extracranial childhood tumor. "Treatment with a dopaminergic toxin, 6-hydroxydopamine, induces an increase of Gadd45g expression and activates the Gadd45g–Map3k4–p38 MAPK pathway, resulting in SRY upregulation in human male neuroblastoma-derived cell line M17 cells." (PMID 25139092, 2014).
osteosarcoma (1 paper, 2024). A usually aggressive malignant bone-forming mesenchymal neoplasm, predominantly affecting adolescents and young adults. "Compared to the sham group, the SNL group had higher gene expression levels of Gadd45g (growth arrest and DNA-damage-inducible 45 gamma) and Fos (FBJ osteosarcoma oncogene), while it had lower gene expression levels of Igf1, Ccl2, Hdac2, Rtn4rl1, Nfkb2, Gpr84, Pik3cg, and Abcc8." (PMID 38790607, 2024).
pituitary tumor (1 paper, 2022). A benign or malignant neoplasm affecting the pituitary gland. "The authors concluded that GADD45G is a powerful growth suppressor controlling pituitary cell proliferation and that it represents the first identified gene whose expression is lost in the majority of pituitary tumors." (PMID 35101009, 2022).
retinoblastoma (1 paper, 2014). A malignant tumor that originates in the nuclear layer of the retina. "The demonstrated increases of gene transcripts related to cellular stress (HSP105) and severe DNA-damage in particular (GADD45G and GADD153) give further evidence of the cellular damage induced by the THPTS-PDT within the retinoblastoma cells." (PMID 24498108, 2014).
rhabdomyosarcoma (1 paper, 2021). A rare aggressive malignant mesenchymal neoplasm arising from skeletal muscle. "The analysis of the transcriptome showed that also in the case of rhabdomyosarcoma, the expression of the GADD45G gene is reduced." (PMID 34360791, 2021).